GLI1 (GLI family zinc finger 1)
Diseases named in the same sentence as GLI1 in open-access papers (continued):
Sharing a sentence is not in itself a finding about the gene and the disease.
gastric cancer (continued). "Since inhibitors for GLI1 and ABCG2 are already available, we predict that these agents, together with CDDP-based chemotherapy, will improve gastric cancer patient survival." (PMID 28404967, 2017). "To further investigate the effect of CD44, Shh, and Gli1 in gastric cancer progression, we analysed the correlations between the level of CD44, Shh, and Gli1 protein and clinicopathological characteristics of GC." (PMID 26839535, 2016). "The results were consistent with the gene expression results, as higher concentrations of cyclopamine (50 and 100 μM) downregulated the protein expression of Gli1 and CXCR4 in the gastric cancer cells." (PMID 24765141, 2014). "This identified that the higher concentrations of cyclopamine (50 and 100 μM) markedly downregulated the gene expression of Gli1 and CXCR4 in the gastric cancer cells." (PMID 24765141, 2014). "Notably, the activation of HH signaling is a key-driver of resistance to 5-FU in LoVo cells and GLI1 and GLI2 knockdown sensitizes gastric cancer and CRC cells to 5-FU." (PMID 40640948, 2025). "Furthermore, we confirmed that G-quadruplex regulators of the GLI1 promoter inhibited gastric cancer progression by downregulating PRKACB, an effector molecule downstream of GLI1." (PMID 40255562, 2025). "Also, NUAK1 can provide the tumor cell with resistance to chemotherapy by upregulating the STAT/GLI1/SOX2 signaling pathway, as indicated by a recent study on gastric cancer." (PMID 41441397, 2025). "The transcription factor GLI1, aberrantly activated in gastric cancer, drives tumor progression, yet no approved inhibitors currently target this molecule." (PMID 40255562, 2025). "Evidently, p-AKT knockdown decreased GLI1 protein expression without affecting SMO levels, and this was associated with depressed growth and migration and enhanced cisplatin sensitivity of gastric cancer cell lines." (PMID 34572373, 2021). "In esophageal squamous cell carcinoma, YAP1 has been shown to upregulate Gli1 30, which is in accordance with our previous study in gastric cancer 30, representing that YAP1 enhances cell migration and proliferation via regulating Gli1 expression through the AKT/mTOR signaling pathway." (PMID 35003351, 2021). "Our data indicates that although there is a crosstalk between the non-classical Integrin αvβ3 pathway and the classical Hedgehog pathway, the activation of GLI1 is almost independent of the Hedgehog pathway in multicellular aggregates of gastric cancer cells." (PMID 31366904, 2019). "As the outcome shows, no matter the expression of HER2 was positive or negative, the survival of gastric cancer patients with positive Gli1 expression is poorer than the patients with negative ones (P = 0.003, P = 0.045)." (PMID 29321573, 2018). "The Gli1 and HER2 both play an important role in the pathogenesis of gastric cancer." (PMID 29321573, 2018). "No matter the expression level of HER2, when the Gli1 expression higher, the prognosis of gastric cancer patients becomes poorer." (PMID 29321573, 2018). "However, only few investigations were done to explore the relationship of Gli1 and HER2 in gastric cancer." (PMID 29321573, 2018). "In order to examine whether Hh signaling pathway was activated in gastric cancer, we determined the expression of SHH and GLI1 in 90 pairs of gastric cancer tissue and adjacent normal tissue samples by immunohistochemistry." (PMID 28399898, 2017). "It will be interesting, though, to reveal the molecule mechanisms by which GLI1 expression is induced in cancer cells with intrinsic tolerance of CDDP, which may provide additional strategies to sensitize gastric cancer cells to chemotherapy." (PMID 28404967, 2017). "The effect of ectopic ABCG2 expression on the IC50 of CDDP was very similar to that GLI1 expression, suggesting that ABCG2 may be the major mediator for regulating drug sensitivity in gastric cancer." (PMID 28404967, 2017).
gastric cancer (continued). "In contrast, exogenous rGal-1 could interrupt the ability of the Gli-1 siRNA to suppress cell invasion and the EMT in gastric cancer cells." (PMID 27835885, 2016). "Intriguingly, loss of Gal-1 in gastric cancer cells resulted in a lack of SHH expression, leading to Hh inactivation, which downregulated SMO and Gli-1." (PMID 27835885, 2016). "In addition, it was revealed that the gene and protein expression levels of Gli1 and CXCR4 were consistently downregulated in the gastric cancer cells when high concentrations of cyclopamine were applied." (PMID 24765141, 2014). "Gli-1 is known to induce expression of proliferative genes such as cyclin D2, FOXM1 and the ras-ERK pathway and to reduce expression of cell cycle repressor p21/CIP1 in gastric carcinoma cell lines." (PMID 17505514, 2007). "In addition, G-quadruplex regulators of the GLI1 promoter inhibited gastric cancer cell proliferation, migration, and invasion by downregulating PRKACB, which provides more options for the clinical treatment of gastric cancer." (PMID 40255562, 2025). "By far, no molecular inhibitor of GLI1 has been approved for the treatment of gastric cancer." (PMID 40255562, 2025). "Interestingly, Gal-1 was found to induce vasculogenic mimicry (VM), an endothelial-independent vascular system that allows blood transportation, through GLI1-mediated upregulation of VM-related molecules, including MMP2, MMP14, and laminin5γ2, in gastric cancer cell lines and tumor xenografts." (PMID 34572373, 2021). "Notably, the expression of p-AKT was positively correlated with GLI1 expression in human gastric cancer tissues, with a stronger correlation in advanced gastric cancer stages; higher levels of p-AKT and GLI1 were also detected in advanced stages of gastric cancer." (PMID 34572373, 2021). "Thus, we concluded that Gli1 and HER2 were overexpressed in gastric cancer tissues." (PMID 29321573, 2018). "However, to the best of our knowledge, the correlation of CD44, Shh, and Gli1 in gastric cancer and their clinicopathological significance have not been reported in the literature." (PMID 26839535, 2016). "Furthermore, we validated the anti-tumor effects of down-regulation of Gli1 in gastric cancer cells and in heterologous subcutaneous caner mice, trying to identify a novel target for therapeutic intervention, especially in HER2-targeted therapy-resistant gastric cancer." (PMID 29321573, 2018). "Accordingly, we concluded that SMO-independent activation of Gli-1, i.e., non-canonical Hh signaling, was at least partially responsible for Gal-1-induced EMT and invasion in gastric cancer cells." (PMID 27835885, 2016). "We found that Integrin αvβ3 not only mediated adhesion of gastric cancer multicellular aggregates to form independent functional units, but also maintained their stem cell-like phenotype by the non-classical pathway Integrin αvβ3/ERK1/2/GLI1." (PMID 31366904, 2019). "To test whether the classical Hedgehog-GLI signaling pathway, in addition to the non-classical pathway Integrin αvβ3/ERK1/2, regulates GLI1 in gastric cancer MCAs, we pretreated BGC823 MCAs and SGC7901 MCAs with Integrin αvβ3 co-stimulator ligand RGD." (PMID 31366904, 2019). "In this study, we found that FOXS1 expression was significantly correlated with GLI1 expression in the STAD tumor dataset but was not correlated with GLI1 expression in the STAD normal dataset, suggesting that GLI1 and FOXS1 may exhibit interplay in gastric cancer." (PMID 30918291, 2019).
glioblastoma (83 papers, 2010 to 2026). The most malignant astrocytic tumor (WHO grade IV). "GLI-1, also known as glioma-associated homologue-1, was first discovered in 1987 as an amplified gene in glioblastoma multiforme." (PMID 37454090, 2023). "Association between low nuclear GLI1 immunoexpression and shorter progression-free survival was observed in human glioblastoma samples." (PMID 37964226, 2023). "PTEN-deficient glioblastomas expressed higher levels of GLI1 and GLI2 mRNA compared PTEN-expressing glioblastomas." (PMID 36010600, 2022). "Of note, USP48 and GLI1 expression levels directly correlate in human glioblastoma specimens, and they are linked to tumor malignancy grade." (PMID 32531973, 2020). "As an effector molecule of the Hedgehog pathway, GLI1 is known to be increased in glioblastomas, and the expression level of GLI1 is strongly associated with patient survival according to the CGGA mRNA array and RNA sequencing data." (PMID 31492002, 2019). "Taken together, our results indicate that overall glioblastoma tumor growth suppression by penfluridol was associated with Akt-mediated inhibition of GLI1." (PMID 28380428, 2017). "Low levels of GLI1 were found to be associated with high expression levels of Cyclin D2 in the glioblastoma samples (p = 0.007)." (PMID 21059263, 2010). "A separate study showed that Gli1, another Hh effector, was silenced by Hes1, a Notch-specific protein that encodes a basic helix–loop–helix (bHLH) transcriptional repressor, in glioblastoma neurosphere lines and primary human glioblastoma lines." (PMID 39766864, 2024). "Thus, in PTEN-deficient glioblastomas, GLI1 expression is driven by both SMO-dependent canonical Hh and PI3K pathways." (PMID 36010600, 2022). "In addition, the resistance of glioblastoma to current therapies is associated with GLI1 because hedgehog-GLI signaling regulates the expression of stemness genes." (PMID 31492002, 2019). "Moreover, Forkhead box M1 (FOXM1) transcriptionally activates the expression of IPO7 to promote the nuclear import of glioma-associated oncogene homolog 1 (GLI1), and this biological process modulates the growth, migration, and invasion of glioblastoma multiforme cells in vitro." (PMID 35588577, 2022). "The elevated promoter methylation status of the GLI1 gene in GBM samples suggests a crucial role for epigenetic regulation in the pathogenesis of glioblastoma." (PMID 41596413, 2026). "We used U-87MG cells as an established in vitro model of glioblastoma that exhibits active HH signaling as indicated by Gli1 expression and nuclear localization." (PMID 40651614, 2025). "The Gli1-targeted NPs can inhibit the tumor-promoting HH pathway and its downstream target genes, thereby alleviating drug resistance and glioblastoma recurrence." (PMID 39339205, 2024). "These Gli1-targeted NPs bind to scavenger receptors on glioblastoma cells and induce dynamin-dependent and caveolae-mediated endocytosis." (PMID 39339205, 2024). "HES1, a downstream target of Notch signalling, modulates SHH signalling in glioblastoma by binding to N-boxes within GLI1's first intron, suppressing its expression and potentially inhibiting the HH cascade." (PMID 39568072, 2024). "GLI-1 had been demonstrated to be overexpressed in multiple human cancers including glioblastoma, osteosarcoma, and rhabdomyosarcoma." (PMID 37304485, 2023). "Meanwhile, miR-326 has been shown to increase effects of curcumin in animal models of glioblastoma through modulation of Shh/GLI1 signaling pathway." (PMID 36100906, 2022). "Previous studies have indicated that IPO7 promoted glioblastoma cell proliferation and migration by increasing the nuclear import of GLI1." (PMID 34650978, 2021). "Despite having observed Gli1 overexpression in our three glioblastoma cell lines, the Shh pathway was active only in U87MG cells." (PMID 34073238, 2021). "The Erbb3, Gli1 and Mdm2 genes are all present in this region, and their amplification is known to have effects in human glioblastoma." (PMID 33435218, 2021).
glioblastoma (continued). "Hes1, a well-known target of Notch signaling, regulate hedgehog signaling in glioblastoma and thereby therapeutic resistance by directly binding to N-boxes located within the first intron of Gli1 and repressing its expression." (PMID 33968932, 2021). "The primary glioblastoma cells (GLI1) and HBL52 cells show a Dp71 cytoplasmic expression with a formation of clusters (R black arrow) and no colocalization signal between Dp71 and lamin B proteins was detected." (PMID 31683640, 2019). "Another example are tumors that depend on specific gene amplification, more precisely on GLI1 gene amplification, such as glioblastoma or rhabdomyosarcoma." (PMID 30158435, 2018). "We observed that penfluridol treatment reduced the expression of GLI1 in all the glioblastoma cells in a concentration-dependent manner." (PMID 28380428, 2017). "Our results showed Akt-mediated suppression of GLI1 with penfluridol treatment in various glioblastoma cell lines." (PMID 28380428, 2017). "On the other hand, overexpression of GLI1 using GLI1 specific plasmid, reduced the growth inhibitory effects of penfluridol, indicating the specificity of penfluridol for GLI1 in glioblastoma cells." (PMID 28380428, 2017). "We found that the GLI1 gene is highly amplified, mutated and deleted in various cancer types, and that the majority of GLI1 gene amplification was detected in ∼10% glioblastoma tumor patients." (PMID 28562331, 2017). "Several recent studies demonstrated the role of sonic hedgehog signaling, specifically GLI1 in glioblastoma progression and the role of GLI1 in imparting stem cells characteristics." (PMID 28380428, 2017). "Overall, our studies established the anti-tumor efficacy of penfluridol against glioblastoma via Akt-mediated suppression of GLI1." (PMID 28380428, 2017). "Of note, our studies indicated that knocking down GLI1 reduced the expression of OCT4 and Nanog showing direct regulation of cancer stem cells by GLI1 in glioblastoma cells." (PMID 28380428, 2017). "It has been reported that glioblastoma tumors develop resistance to temozolomide therapy due to overexpression of GLI1, and that GLI1 imparts stem cell like properties to cancer cells rendering them ineffective to chemotherapy." (PMID 28380428, 2017). "It has also been established that resistance of glioblastoma tumors to current therapies are related to overexpression of GLI1." (PMID 28380428, 2017). "In our current study, we demonstrated that penfluridol treatment inhibited the growth of glioblastoma cells by Akt-mediated inhibition of GLI1." (PMID 28380428, 2017). "Patients with glioblastoma containing high or low expression of Gli1 showed a considerably different prognosis in the CGGA mRNA array dataset and RNA sequencing dataset." (PMID 27894350, 2016). "Binding of SHH-N to PTCH1 in the embryonic neural tube results in release of PTCH1-regulated inhibition of Smoothened (SMO) and regulation of the expression of SHH target-genes, like the glioblastoma (Gli) protein family members, Gli1, Gli2, and Gli3." (PMID 24865218, 2014). "Fourteen high grade astrocytomas (grades III and IV) were assessed for Cyclin D2 and GLI1 expression: only 2 glioblastomas (grade IV) co-expressed Cyclin D2 and GLI1 at high levels." (PMID 21059263, 2010). "A truncated GLI1 splice variant (tGLI1) in which all of exon 3 and part of exon 4 were skipped, was not expressed in normal cells but was highly expressed in glioblastoma multiforme (GBM) and other cancer cells." (PMID 37009804, 2023). "Also, GLI1 mRNA transcription was decreased with the SMO inhibitor, sonidegib, in PTEN-deficient glioblastoma." (PMID 36010600, 2022). "RT-qPCR showed Gli1 overexpression in glioblastoma cell lines." (PMID 34073238, 2021).
glioblastoma (continued). "Interestingly, AMPK activity has been shown to regulate the ability of β‐TrCP to recognize and ubiquitinate Gli1, a transcription factor that is involved in regulating glioblastoma tumorigenesis." (PMID 30428154, 2019). "The nuclear import mechanism of GLI1 has been described for glioblastoma multiform cells." (PMID 29849100, 2018). "Interestingly, GLI1 was found to be up-regulated in glioblastoma and responsible for chemo-resistance." (PMID 28380428, 2017). "Our current studies established regulation of GLI1 by Akt in glioblastoma cells." (PMID 28380428, 2017). "Analysis of patient-derived glioblastoma neurospheres and tumor cell lines revealed higher abundance of N’ΔGLI1 compared to the wild-type protein suggesting the absence of two inhibitory regions located in the full-length GLI1 N-terminus: an N’ degron and SUFU-binding site." (PMID 32957513, 2020). "Hh signaling appears to be active in glioblastoma multiforme (GBM)-derived neurospheres and glioma stem cell cultures (gliomaspheres), as they express GLI1, PTCH1, SMO and SHH." (PMID 26270676, 2015). "In human glioblastoma, there exists a positive correlation between the expression levels of USP48 and Gli1." (PMID 40034124, 2025). "To evaluate the effect of the identified GANT61 analogs on cancer cell viability, we first assessed the expression of GLI1 and GLI2 in two human glioblastoma cell lines, U87MG and T98G, previously shown to be GANT61-sensitive and GLI1-dependent." (PMID 38999049, 2024). "Knockdown of PTEN by siRNA increased GLI1 and GLI2 mRNA transcription in PTEN-expressing glioblastomas, suggesting that the PI3K pathway regulated GLI1 and GLI2 expression." (PMID 36010600, 2022). "In an animal model with glioblastoma, the treatment with LDE225 decreased the tumor size with downregulation of GLI1, GLI2, PTCH1, and SMO." (PMID 34642915, 2022). "Stimulation of VIP/PACAP receptors triggers the cAMP/PKA axis, that reduces migration and invasion of glioblastoma cells via the inhibition of the PI3K/Akt and the Shh/GLI1 signalling routes." (PMID 34616669, 2021). "In human primary glioblastoma initiating cells, sonidegib reduces levels of GLI1, GLI2, PTCH1, and PTCH2 messenger ribonucleic acid (RNA) and protein, as well as GLI1 and GLI2 translocation into the nucleus." (PMID 32973971, 2020). "The third isoform tGLI1 is a cancer-associated form of GLI1, and is not detected in normal cells but is found in glioblastoma multiforme (GBM) and other cancers." (PMID 32245491, 2020). "In glioma-initiating cells and glioblastoma, both OCT-4 and GLI1 are overexerted and this axis maintains the stemness phenotype by binding to the SPP1 gene." (PMID 32429463, 2020). "As several clinical trials using GLI1 inhibitors, like GANT61, have a limitation with respect to crossing the blood–brain barrier and causing unwanted adverse effects, therefore, PFD may be a potential candidate drug for glioblastoma treatment, especially in combination with TMZ." (PMID 31492002, 2019). "The transcriptomics data on 149 clinical cases of The Cancer Genome Atlas-Glioblastoma (GBM) database showed a robust correlation between PTCH1 and GLI1 mRNA expression as an indication of the canonical Shh pathway activity in this malignancy." (PMID 29558958, 2018). "Penfluridol treatment suppressed the phosphorylation of Akt at Ser473 and reduced the expression of GLI1, OCT4, Nanog and Sox2 in several glioblastoma cell lines in a concentration-dependent manner." (PMID 28380428, 2017). "The levels of GLI1 and OCT4 mRNAs were determined in the same samples of normal brain, pilocytic astrocytomas and glioblastomas analyzed for SPP1 expression." (PMID 28030801, 2017). "Self-renewal, survival and tumourigenicity of CD133+ glioblastoma CSCs require SMO and GLI1 activity, as shown by their inhibition with cyclopamine and RNA interference (Refs 75, 84)." (PMID 25660620, 2015). "GLI1 was identified as an amplified gene in a human glioblastoma (GBM) cell line, D-259 MG in 1987." (PMID 21119888, 2010).